NGF (nerve growth factor)
Diseases named in the same sentence as NGF in open-access papers (continued):
Sharing a sentence is not in itself a finding about the gene and the disease.
mastocytosis (4 papers, 2017 to 2023). A clonal myeloproliferative neoplasm characterized by the proliferation and accumulation of neoplastic mast cells in one or multiple organs or organ systems. "Patients with mastocytosis exhibit elevated serum levels of NGF and NT-4, which are related to the load of MCs." (PMID 37998739, 2023). "A synergistic anti-apoptotic effect has been observed for NGF/SCF and NT-3/SCF in human MCs; thus, determining whether TRK signaling cooperates with KIT mutations in the induction of SM remains an important aspect for understanding mastocytosis development." (PMID 34063170, 2021). "None of >20 C57BL/6J mice transplanted with dTRKA-modified primary Lin-cells developed SM, in contrast with the development of SM in 43% of mice transplanted with TRKA/NGF, suggesting that ERK may be important for mastocytosis development." (PMID 34063170, 2021).
myopia (4 papers, 2022 to 2025). "Herein, we report the differential expression of NGF, BDNF, and related receptors between myopia and high myopia, and their association with NO/nitrites/iNOS/NOX1/4, KEAP1/NRF2, and some epigenetic factors (HDMT3α, HD1), as observed from studies on aqueous and myopic LEC." (PMID 40650128, 2025). "Furthermore, the imbalance between oxidative stress, NGF, and BDNF in human high myopia, which showed an association with total nitrite levels, was also observed." (PMID 40650128, 2025). "Moreover, a positive correlation has been observed between tear NGF levels and the degree of myopia corrected with SMILE." (PMID 40649793, 2025). "Some studies focused on the role of TGF-β in myopia development, being a key regulator of scleral remodeling, which can contribute to eye elongation and myopia progression, prospecting the hypothesis that NGF and BDNF might also act as additional remodeling factors." (PMID 40650128, 2025). "Herein, we prospect the contribution of NGF and BDNF, throughout transcript and receptors modulation, in myopia and high myopia, prospecting their involvement at both inflammatory and neuroprotective levels." (PMID 40650128, 2025). "A trial involving rhesus monkeys evaluated nerve regeneration, as well as NGF mRNA and protein expression, following laser in situ keratomileusis (LASIK) to correct −8.00 diopters of myopia." (PMID 40649793, 2025). "For both procedures, the high myopia group showed a slightly higher but non-significant NGF concentration than the low-moderate myopia group at all time points." (PMID 40165267, 2025). "This aspect is not new as cataract and myopia show common light exposure, and NGF was found to protect corneal cells and retina from the UV light effects, both in vitro and in experimental models." (PMID 40650128, 2025). "Another study, however, using small incision lenticule extraction for the treatment of myopia, also found no changes in tear film NGF levels neither at one week nor at three months after surgical treatment." (PMID 35886858, 2022).
neuroma (4 papers, 2022 to 2024). A tumor that grows from a nerve or is composed of nerve cells and nerve fibers. "Several hypotheses have been postulated for the pathogenesis of neuroma-related pain, including alpha-smooth muscle actin, neural fiber structural changes, nerve growth factor, and/or sensitization of the affected nerve." (PMID 36465207, 2022). "Studies have pinpointed crucial factors, including nerve growth factor (NGF), brain-derived neurotrophic factor (BDNF), and various cytokines, as key players in the formation and maintenance of neuromas." (PMID 38672500, 2024).
Optic neuropathy (4 papers, 2020 to 2025). "This study demonstrates that topical rh-NGF is neuroprotective to RGCs and their axons in an optic neuropathy model of pONT." (PMID 32099056, 2020). "The capability of imaging RGC apoptosis in vivo would pave the way to evaluate NGF therapy in patients with all kinds of optic neuropathy." (PMID 32099056, 2020). "Previously, it has been shown that intravitreal administration of exogenous NGF exhibits neuroprotective effects by increasing RGC survival seen in various animal models of optic neuropathy, including ON axotomy, OHT glaucoma, and diabetic retinopathy." (PMID 32099056, 2020).
Pain (4 papers, 2011 to 2025). An unpleasant sensory and emotional experience associated with actual or potential tissue damage, or described in terms of such damage. "Nerve growth factor (NGF) serves as a primary mediator in the development of neuropathic pain; it induces the upregulation of CGRP and substance P in sensory neurons, increasing the sensitivity of nociceptors." (PMID 40362812, 2025). "This is the first study to identify an NGF/ERK/ acetylated histone H3 (Ac-H3) signaling axis in the CSF-CN as a central mediator of neuropathic pain through epigenetic modulation." (PMID 41245866, 2025).
pancreatic ductal adenocarcinoma (4 papers, 2023 to 2025). An infiltrating adenocarcinoma that arises from the epithelial cells of the pancreas. "In pancreatic ductal adenocarcinoma, a hyperglycemic tumor microenvironment enhances tumor cell proliferation, invasion and perineural invasion by upregulating NGF expression and strengthening the functional crosstalk between cancer cells and surrounding nerves." (PMID 41471293, 2025). "Similarly, in pancreatic ductal adenocarcinoma, norepinephrine promotes β2-ARs-dependent nerve growth factor (NGF) secretion." (PMID 36707854, 2023). "In pancreatic ductal adenocarcinoma, the peripheral axons supply serine to provide metabolic support for tumor growth in nutrient-poor environments, while serine-deprived conditions can conversely promote tumor innervation via the translation and secretion of the nerve growth factor (NGF)." (PMID 38334648, 2024).
psychosis (4 papers, 2018 to 2025). "Vitamin D regulates the release of nerve growth factor (NGF), which is one of the essential molecules for the survival of hippocampal neurons and cortical neurons and is also known to reduce the risk of psychosis in children with chromosome 22q11.2 deletion." (PMID 39781525, 2025). "Decreased NGF in CSF (p = 0.038) in patients with psychosis was reported in one study." (PMID 37692299, 2023).
respiratory syncytial virus infection (4 papers, 2009 to 2024). "Increased NGF levels in BALF of infants after respiratory syncytial virus infection is associated with increased preprotachykinin gene expression in airways, supporting the possibility that NGF contributes to altered SP expression in early life." (PMID 19750110, 2009).
retinal disease (4 papers, 2014 to 2024). "On the other hand, both astrocytes and Müller cells are source of NGF and in turn can utilize NGF by means of trkANGF expression, as reported in human retinal diseases and experimental models." (PMID 30811468, 2019). "In line with recent and the herein presented data, we propose E-reeler mice as a good “retinal disease” model to explore the cross-talk between NGF and Reelin." (PMID 24627687, 2014).
Rett syndrome (4 papers, 2011 to 2026). A severe neurodevelopmental disorder affecting the central nervous system. "For instance, previous studies have demonstrated a reduction in the hippocampal expression of the nerve growth factor associated with a tendency to increased hippocampal BDNF levels in another mouse model of developmental disorder, the Rett syndrome." (PMID 37566006, 2023). "Also, NGF levels are reduced in an animal model of Rett Syndrome and in the serum of medication-naïve patients with SZ." (PMID 24736721, 2014).
sarcoidosis (4 papers, 2010 to 2025). Sarcoidosis is a multisystemic disorder of unknown cause characterized by the formation of immune granulomas in involved organs. "In line with our previous report, NGF was significantly elevated in sarcoidosis patients (14.8; 6.1-22.6 pg/ml) as compared to healthy subjects (4.7; 2.0-17.0 pg/ml) (p < 0.01)." (PMID 21059230, 2010). "The sarcoidosis patients showed significantly enhanced NT-3 and NGF levels in BALF, whereas BDNF was undetectable in both patients and controls." (PMID 21059230, 2010). "We have recently reported higher levels of nerve growth factor (NGF) in the airways of patients with sarcoidosis as compared to healthy subjects." (PMID 21059230, 2010). "Despite the lack of detectable levels of BDNF in BALF, we could detect both BDNF and its receptor in the granulomas and airway cells in sarcoidosis by immunohistochemistry in a similar fashion as for NGF and NT-3." (PMID 21059230, 2010). "In addition, Ricci and co-workers have demonstrated that immune cells, such as alveolar macrophages and T-lymphocytes, retrieved from BAL from sarcoidosis patients, express NGF, NT-3 and BDNF to a larger degree than BAL cells from healthy subjects." (PMID 21059230, 2010). "We confirm and extend these results by showing positive NGF, BDNF and NT-3 immunostaining in alveolar macrophages present within the lung parenchyma of sarcoidosis patients." (PMID 21059230, 2010). "To elucidate the cellular targets for NGF, BDNF and NT-3 within the airways in sarcoidosis, we studied the presence of the corresponding neurotrophin receptors, TrkA, TrkB and TrkC, in lung biopsies." (PMID 21059230, 2010). "This study shows that not only the NGF protein, but also NT-3 protein, was elevated in BALF from sarcoidosis patients as compared to healthy subjects, while BDNF protein levels were undetectable in both healthy subjects and sarcoidosis patients." (PMID 21059230, 2010). "Differences between subgroups of sarcoidosis patients was not seen for NGF in this study, but has been indicated in one of our previous studies, including a larger study population." (PMID 21059230, 2010).
small-fiber neuropathy (4 papers, 2022 to 2024). "The deficit of nerve growth factor (NGF) can lead to the development of small fiber neuropathy." (PMID 39408723, 2024). "An impairment in NGF signaling may therefore support the “small-fiber neuropathy” described in humans, while a VEGF signaling impairment may affect angiogenesis, and both of these factors may be responsible for delayed wound healing in diabetic mice." (PMID 35386010, 2022).
Stress urinary incontinence (4 papers, 2013 to 2023). Involuntary urine leakage synchronous with exertion, or actions such as sneezing, or coughing. "Similarly to the degree of NGF expression in association with the OAB, the degree of NGF expression in the neuronal voiding centers (PMC and vlPAG) and the dorsal horn of the L5 spinal cord was significantly increased in an animal experimental model of stress urinary incontinence." (PMID 24160992, 2013).
alcohol addiction (3 papers, 2012 to 2023). "Latest research highlights the importance not only of gene expression itself but also of epigenetic regulation of genes encoding for neurotrophic factors, including nerve growth factor (NGF) and brain-derived neurotrophic factor (BDNF), in alcohol addiction." (PMID 36834747, 2023). "The current data extend our understanding of the different patterns of neuroadaptation, specifically of BDNF and NGF, within two key brain regions (hippocampus and frontal cortex) in an animal model of late-stage sustained alcohol addiction." (PMID 26930631, 2016). "BDNF, a member of the nerve growth factor (NGF) family, and its receptor TrkB are widely distributed throughout the brain, and have a role in synaptic plasticity associated with alcohol addiction and several psychiatric disorders." (PMID 23060746, 2012).
allergic conjunctivitis (3 papers, 2009 to 2025). "On the ocular surface, NGF has been studied in the context of allergic conjunctivitis, NK, immune and infectious keratitis, DED, corneal transplant, cataract, and refractive surgery." (PMID 40649793, 2025). "NGF has been extensively studied in both experimental and clinical contexts for its role in ocular surface diseases, including allergic conjunctivitis, NK, immune and infectious keratitis, DED, and corneal transplantation, cataract, and refractive surgeries." (PMID 40649793, 2025). "During allergic conjunctivitis, NGF is released by conjunctival epithelial and immune cells." (PMID 40649793, 2025). "NGF is a potential therapeutic agent for various ocular surface diseases, particularly those involving epithelial regeneration (e.g., NK), inflammation (e.g., allergic conjunctivitis and immune keratitis), infection (e.g., HSV keratitis), and post-surgical corneal wound healing." (PMID 40649793, 2025). "Future studies, particularly randomized controlled trials, are warranted for a range of conditions in which evidence for NGF use remains limited, such as DED, refractive surgery, and allergic conjunctivitis, among others." (PMID 40649793, 2025).
autism spectrum disorder (3 papers, 2022 to 2025). A spectrum of developmental disorders that includes autism, and Asperger syndrome. "In pediatric neurology, NGF is progressively recognized as a key player in the pathophysiology of various brain disorders affecting children, such as autism spectrum disorders (ASD), attention deficit hyperactivity disorder (ADHD), and pediatric epilepsy." (PMID 39056738, 2024). "The mechanisms of NGF-induced neuronal differentiation are well established, but its effect on mitochondria in autism spectrum disorder (ASD) is still unclear." (PMID 36233217, 2022). "First, NGF could be upregulated in paediatric patients, e.g., children with autism spectrum disorder, probably because of the positive correlation between NGF and the overall developmental status of children." (PMID 40783715, 2025). "Excessive brain development and structural changes in the brains of children affected by autism spectrum disorders, moreover, could be backed by the neurotrophic action of NGF." (PMID 39056738, 2024).
autoimmune thyroiditis (3 papers, 2023 to 2025). "Despite these findings, further research is necessary to completely understand the exact association between NGF and autoimmune thyroiditis and its potential implications." (PMID 37998739, 2023).
autonomic neuropathy (3 papers, 2003 to 2025). An inherited or acquired peripheral neuropathy affecting the autonomic nervous system. "Mutations in the gene of another neurotrophin, NGF (OMIM* 162030), are associated with hereditary sensory and autonomic neuropathy." (PMID 40003962, 2025). "Interestingly, the nerve growth factor signaling cascade (NGF/TrkA) is essential for sensory neuron survival and mutations in both NGF and its receptor, TrkA, encoded by NTRK1, lead to sensory and autonomic neuropathy." (PMID 27923065, 2016).
behavioral disorders (3 papers, 2017 to 2022). "In contrast, GM1/2/3 showed weaker effects on the behavioral disorders of PD mice than MA, but GM1/2/3 significantly inhibited the occurrence of apoptosis, increased expression of NGF and its receptors, and enhanced proteins levels of TH and DAT." (PMID 32842556, 2020).
brain cancer (3 papers, 2023 to 2024). A primary or metastatic malignant neoplasm affecting the brain. "Our interest in ATF5 and its potential role in brain cancers first arose from studies to identify genes regulated by nerve growth factor (NGF) in the context of neuronal differentiation." (PMID 36831248, 2023). "Obviously, one could assume that the NGF might play a role in brain cancers." (PMID 38791953, 2024). "Irradiation-induced exosome-specific changes were found to trigger nerve growth factor (NGF)-tyrosine protein kinase (Trk) A and focal adhesion kinase (FAK) signaling pathways in brain cancer patients." (PMID 37849740, 2023).
cholangiocarcinoma (3 papers, 2010 to 2025). A carcinoma that arises from the intrahepatic biliary tree (intrahepatic cholangiocarcinoma) or from the junction, or adjacent to the junction, of the right and left hepatic ducts (hilar cholangiocarcinoma). "In cholangiocarcinoma (CCA) patients from Caucasian regions, NGF and TrkA are rarely detected in malignant epithelial cells, even though PNI is a classical route of metastasis for CCA, highlighting the potential role of other cell types in the microenvironment." (PMID 40783715, 2025).
chronic myeloid leukemia (3 papers, 2011 to 2022). "We have previously shown that NGF-TrkA signaling partially rescues TrkA expressing Bcr-Abl transformed chronic myelogenous leukemia (CML) cells, such as K562, and Meg-01, from cell death induced by a potent inhibitor of Bcr-Abl tyrosine kinase, imatinib mesylate (imatinib)." (PMID 21501463, 2011).
Cirrhosis (3 papers, 2015 to 2024). A chronic disorder of the liver in which liver tissue becomes scarred and is partially replaced by regenerative nodules and fibrotic tissue resulting in loss of liver function. "In contrast to NGF, p75NTR mRNA expression was higher in subjects with cirrhosis compared to patients with fibrosis only, with a correlation between p75NTR expression and the reactivity of activated HSCs, similar to other in vitro experimental fibrosis studies." (PMID 25816145, 2015). "Concerning the liver, the NGF has been found in rat and human HSCs both in normal liver and in CCl4- or HCV-induced cirrhosis." (PMID 34064584, 2021). "A positive correlation between p75NTR and NGF gene expression was observed in livers with mild to moderate fibrosis, though not in cases of severe fibrosis and cirrhosis." (PMID 25816145, 2015).
contact dermatitis (3 papers, 2015 to 2022). An inflammatory skin condition caused by direct contact between the skin and either an irritating substance or an allergen. "On the other hand, our results are surprising given that in induced human contact eczema elevated NGF levels and a sensitization of itch but not pain evoked by BAM8–22 and β-ALA were described." (PMID 34728705, 2021).
cyst (3 papers, 2010 to 2021). A sac-like closed membranous structure that may be empty or contain fluid or amorphous material. "The hyperactivation of ovarian sympathetic nerves in rats with EV-induced PCOS is related to an over production of NGF suggesting that activation of this neurotrophic-neurogenic regulatory loop is a component of the pathological process by which EV induces cyst formation and anovulation in rodents." (PMID 20723258, 2010). "NGF signaling is also elevated in women with PCOS, while increased NGF signaling causes mice to show signs of PCOM, with a higher number of atretic antral follicles, without displaying cyst formation—the phenotype we also observed in Abhd2–/– females." (PMID 34568325, 2021).
degenerative disc disease (3 papers, 2014 to 2025). "Increases in the active form of NGF have been directly linked with progression of degenerative joint and degenerative disc disease, and anti-NGF therapies have had some success in pain alleviation." (PMID 25196344, 2014).
delirium (3 papers, 2023 to 2025). A disorder characterized by confusion; inattentiveness; disorientation; illusions; hallucinations; agitation; and in some instances autonomic nervous system overactivity. "Our proteomics analysis measures NGF as increased in patients that will develop delirium, and it has been shown that NGF is increased in the CSF of patients with AD." (PMID 37759795, 2023). "Serum NGF levels were significantly elevated in AUD patients, especially in those with prior delirium." (PMID 38928583, 2024).
demyelinating disease (3 papers, 2021 to 2023). A broad group of disorders that affect the myelin sheaths that cover the neurons. "In addition to unveiling the molecular mechanism linking NGF to oligodendrogenesis, our study may also have therapeutic implications for demyelinating diseases, such as MS." (PMID 33669304, 2021). "Additionally, further characterization of NGF-signaling downstream effectors could lead to the identification of additional therapeutic targets to be exploited, in synergy with miR-219, in the treatment of demyelinating diseases." (PMID 33669304, 2021).